TLR2 (toll like receptor 2)
Diseases named in the same sentence as TLR2 in open-access papers (continued):
Sharing a sentence is not in itself a finding about the gene and the disease.
cancer (continued). "A recent publication has clearly shown that through activation of TLR2 and TNF-alpha, versican can be accelerated to offer an appropriate environment for cancer cells to survive and pursue a metastatic spread." (PMID 25859560, 2015). "Pancreatic adenocarcinoma upregulated factor (PAUF), an endogenous ligand of TLR2 and TLR4, is overproduced in certain types of cancer including pancreatic cancers." (PMID 25723737, 2015). "On the other hand, TLR2 and TLR4 protein levels shown were focused on normal and cancerous tissues in relation to healthy patients and cancer patients." (PMID 25547486, 2014). "The potential use of the immunostimulatory properties of TLR agonists, particularly TLR2, TLR3, TLR4, TLR7/8, and TLR9, has been investigated in cancer immunotherapy." (PMID 25309546, 2014). "However, the cause of TLR2 overexpression in human cancers has not been elucidated." (PMID 23866094, 2013). "TLR2 agonist MALP-2, a 2 kDa synthetic lipopeptide with macrophage-stimulatory activity, is currently in use as a cancer immunotherapy." (PMID 24098333, 2013). "Whereas, the effective cancer adjuvant, BCG-CWS, activates not only TLR2, but also TLR4 and NOD2 receptors." (PMID 21533081, 2011). "The anti-cancer activity of BCG-CWS operates partly through TLR2 signal, hence, we investigated the adjuvant activity of synthetic TLR2/TLR6 ligands derived from Staphylococcus aureus, 16 S-[2,3-bis(palmitoyl)propyl]cysteine (Pam2) lipopeptides." (PMID 21533081, 2011). "Ligands of TLR2 and TLR5 also induced migration of NCI-H292 cells, suggesting that both cancer growth and spreading can be affected by certain TLR signals." (PMID 18167552, 2008). "In addition, cancer cell–derived SAA1 promotes the recruitment of MDSCs and their differentiation from GMPs via TLR2/4 signaling, while also inducing IL-1β secretion by MDSCs." (PMID 41029721, 2025). "Interestingly, TLR2 is expressed on OSA cell lines, and we and others have demonstrated that TLR2 promotes cancer resistance to chemotherapy." (PMID 41375047, 2025). "BGN has been reported to bind both TLR2 and TLR4 in various cell types, including cancer cells." (PMID 41465449, 2025). "The GSEA revealed that cancer-related gene modules were remarkably enriched in patients with upregulated TLR4, TLR2, TLR1 and PYCR1 (TLR4upTLR2upTLR1upPYCR1up) compared with patients with a downregulated expression of these markers (TLR4downTLR2downTLR1downPYCR1down)." (PMID 41254241, 2025). "High expression levels of TLR2 and FADD in cancer cells could indicate a favorable response to treatments targeting these pathways, making them promising candidates for personalized immunotherapy strategies." (PMID 39669578, 2024). "Nevertheless, in cancer cells, the presence of a similar protective mechanism to prevent apoptosis triggered by TLR2 activation appears to be absent." (PMID 39669578, 2024). "According to the KEGG analysis, CHST11 may participate in PD‐L1 expression and PD‐1 checkpoint pathway in cancer by regulating genes TICAM2, LAT, TLR2, CD4, STAT3, NFKBIE and CD3D." (PMID 36062845, 2023). "TLR2 does not just impact cancer cells directly; it also plays a significant role in cancer progression through its influence on the immune system." (PMID 38203626, 2023). "In addition, the expression levels of IL-6, IL-17, TNF-α,IL-12β, TLR-2, and TLR-4 as well as miR-21 and miR-31 showed a significant increase in the cancer group." (PMID 38075864, 2023). "Thus, TACAs have been coupled with different compounds, including zwitterionic polysaccharide A1 (PSA1), Toll-like receptor 2 (TLR2) ligand, Pam3CysSerK4, and T-cell peptide epitopes, to develop self-adjuvant multi-component cancer vaccines." (PMID 35806376, 2022). "As a TLR2 agonist, HP-NAP can also drive a pro-allergic Th2 response toward a Th1 response or induce the pro-inflammatory Th1 responses and CTL responses against cancer." (PMID 36613542, 2022).
cancer (continued). "Additionally, TLR2 and TLR6 expression were found to be poor predictive markers for five distinct forms of cancer, respectively." (PMID 35801728, 2022). "The data herein demonstrate a role for TLR2 in modulating the expression of PDL1 in HNSCC models and suggest that microbiota may directly modulate immunosuppression in cancer cells." (PMID 34638266, 2021). "Alternatively, angiogenesis in cancer could be affected by biglycan through the stabilization HIF-2α, which is induced by TLR2 interaction with biglycan and results in the induction of erythropoietin (Epo) synthesis and polycythemia." (PMID 34917515, 2021). "Another study has determined peptidoglycan (PGN) from the infectious bacterium Staphylococcus aureus (PGN-SA) led to the activation of Toll-like receptor 2 (TLR2) in MDA-MB-231, leading to an increase of invasiveness and adhesiveness of the cancer cells in vitro." (PMID 34827233, 2021). "Immunohistochemistry-based studies in tongue SCC show a range of TLR2, 4 and 5 expression in OSCC cells and suggest that the amount of TLR expression in carcinoma cells may positively correlate with more advanced tumors and worse outcomes." (PMID 35048056, 2021). "The immunostaining of TLR2 was not possible to interpret appropriately in 6.1% of patients due to technical staining problems or due to missing cancer tissue." (PMID 32424768, 2020). "The TLR2/HMGB1 axis promotes natural killer (NK) and cancer stem cell activation." (PMID 30306212, 2019). "TLR2 and TLR4 agonists, Coley toxin (mixture of killed Streptococcus pyogenes and Serratia marcescens bacteria) and Bacillus Calmette-Guerin have become long-used therapeutic drugs against cancers." (PMID 28216575, 2017). "Although the relationship between cell-bound TLR2 and its release as a soluble form is not clear-cut, the observed higher concentrations of sTLR2 in the (small) group of patients with an underlying malignancy may reflect the increased expression of TLR2 as seen in some forms of cancer." (PMID 25406630, 2014). "TLR2 and TLR4 are major TLRs and have been actively investigated in inflammation and cancer." (PMID 24376595, 2013). "TLR2 in MDA-MB-231 cells were actively triggered by peptidoglycan (PGN) from infectious bacterium Staphylococcus aureus (PGN-SA), resulting in the promoted invasiveness and adhesiveness of the cancer cells in vitro." (PMID 20520770, 2010). "As a role for secreted Hsp70 in MΦ M2 polarization has not been described previously, the finding that cancer-secreted Hsp70 controls MΦ polarization through TLR2 and MerTK receptors establishes a new immunosuppressive molecular communication mechanism between cancer cells and MΦ mediated by Hsp70." (PMID 39941817, 2025). "Whilst our pilot study in an Australian White population that explored a more comprehensive panel of immune and pain-related SNPs revealed risk of severe GI adverse effects after 5-FU was related to TNF and toll-like receptor 2 (TLR2) SNPs, together with cancer type, a non-genetic predictor." (PMID 37162533, 2023). "Moreover, silencing of TLR4 but not TLR2 markedly recovered disialyl Lewisa or sialyl 6-sulfo Lewisx expression on the cancer cell surface." (PMID 32050430, 2020). "It is possible that TLR2 has a greater impact on body weight, that it interacts with the modeling drug, and that changes in body weight and related symptoms do not directly reflect the severity of the cancer." (PMID 32256204, 2020). "Although several pathways are involved in this phenomenon, and the exact mechanisms have not been completely clarified, TLR2 may play a role by mediating both cancer cell-intrinsic and extrinsic mechanisms." (PMID 33321934, 2020).
cancer (continued). "Furthermore, TLR2 silencing enhanced the activation of YAP(the rational of ratio of phosphorylation YAP to total YAP increased) in HMGB1 stimulated CD133− cancer cells, suggesting that YAP is downstream of HMGB1-TLR2 signaling to induce CD133− cancer cells dedifferentiation." (PMID 31558702, 2019). "Inhibition of cleavage of TLR2 by ADAM17 may or may not be helpful for either cancer or inflammatory processes as soluble TLR2 ectodomain can negatively regulate TLR2 activation by behaving as a decoy receptor." (PMID 29230082, 2017). "We identified Toll-like receptor 1 (TLR1), TLR2, TLR4 and TLR8 gene expression levels and downstream gene, i.e., interleukin-6 (IL-6), IL-8, interferon-α (IFN-α) and myeloid differentiation primary-response protein-88 (MyD88), expression levels in CRC patients and in cancer cell lines." (PMID 25547486, 2014). "We are firmly convinced that a deeper understanding of the multifaceted activity played by TLR2 in cancer cells, immune cells, and in the TME could lead to strong improvements in medical oncology, posing the foundations for the development of new combined anti-cancer treatments." (PMID 33321934, 2020). "Furthermore, TLR2 (Toll like receptor 2) was upregulated by EPS116, and the CT26 cells with TLR2 knockdown were found to be insensitive to EPS116, suggesting that the anti-cancer activity of EPS116 may be TLR2-dependent." (PMID 29079852, 2017). "In comparison, two prototypical particulate β-glucans, one isolated from I. obliquus and one from Saccharomyces cerevisiae (zymosan), are agonists for Dectin-1 but not TLR2 or TLR4, and are unable to trigger anti-cancer functions of macrophages." (PMID 38396285, 2024). "The roles of immune and carcinoma cell surface TLR2 and TLR4 in inflammation and immunosuppression are discussed first, followed by non-inflammatory cell-intrinsic carcinoma cell TLR functions." (PMID 35048056, 2021). "Assessing putative cell surface receptors (TLR2 and TLR4) binding with extracellular HMGB1, we found that TLR2, but not TLR4, was upregulated in the CD133− cancer cells when treated with HMGB1+ irradiation cells or rhHMGB1." (PMID 31558702, 2019). "Although previous reports showed that TLR2 and TLR4 are involved in cell migration and invasion, there has been no data about the ligands of cancer cells for TLR2 and TLR4." (PMID 31034495, 2019). "TLR2/1 agonist Pam3CSK4 consistently stimulated A2a expression in five out of six OSCC cell lines with high TLR2 levels, but not in TLR2-low immortalized oral keratinocytes or in UMSCC19 carcinoma cells." (PMID 29467931, 2018). "Given this, we hypothesised that TLR1, TLR2, TLR3, TLR7, TLR8, and TLR9 would be involved in a negative regulatory mechanism mediated by TLR8-AS1 that contributes to the maintenance of cancer stem cell features." (PMID 35801728, 2022). "However, they did not observe significant increases in TLR2 expression in the subsequent progression to adenocarcinoma, with TLR1 and TLR6 showing decreased expression levels in carcinomas when compared with premalignant epithelium." (PMID 33922955, 2021). "Furthermore, these authors found TLR2 and TLR4 overexpression in intestinal metaplasia, independent of the H. pylori status, and in the dysplasia/cancer sequence." (PMID 25873761, 2015).
bacterial infection (183 papers, 2005 to 2026). "TLR4 and TLR2 are identified as key receptors participating in pathogenic inflammatory responses under bacterial infection." (PMID 40963927, 2025). "The TLRs responses against commensals should be tightly regulated to maintain tissue homeostasis but TLR2 deficiency predisposes the hosts to bacterial infections, leading to disease exacerbations." (PMID 38814518, 2024). "TLR2 and 4 classically recognize bacterial ligands and recurrent low grade bacterial infections have been linked to AS but also sterile activators of those TLRs have been found to be relevant in AS development." (PMID 36723728, 2023). "In crustaceans, the TLR2-MyD88 pathway regulates the immune response to pathogenic bacterial infections." (PMID 36290752, 2022). "The TLR2 rs3804099 polymorphism has been connected to altered host immunity against bacterial infection." (PMID 34322122, 2021). "Abundant studies proposed that TLR2 polymorphisms were involved in bacterial infections and various diseases." (PMID 32648572, 2020). "DNA methylation also contributes to inflammatory processes, with hypomethylation of the promoter site of the Toll-like receptor-2 (TLR2) gene being associated with a pro-inflammatory response to bacterial infection in bronchial epithelial cells." (PMID 30131827, 2018). "In the literature, studies indicated that TLR2 is crucial for inflammatory bone loss in response to bacterial infection." (PMID 29995146, 2018). "There was also a moderate positive correlation between the expression Myd88-Tnfrsf11 and Tlr2-Myd88, suggesting the relevance of Tlr2-Myd88 in bone loss due to bacterial infection." (PMID 29995146, 2018). "TLR2 represents one of important sensors to pathogens and TLR2 deficiency impairs host defense against bacterial infection." (PMID 28270814, 2017). "In this study, we investigated the extent to which TLR2 contributes to the host innate response against the bacterial infection using TLR2-deficient mice." (PMID 24058538, 2013). "For instance, deficiency of TLR2 resulted in uncontrolled bacterial growth and increased susceptibility to bacterial infection in TLR2 KO mice." (PMID 22132240, 2011). "Furthermore, the TLR2 signalling pathway plays a prominent role in modulating macrophage differentiation to either M1 or M2 after pathogenic bacterial infection." (PMID 35355723, 2022). "Notably, melatonin resists pathogenic bacterial infections in vivo by various pathways, such as NF-κB, TLR2/4, and ROS." (PMID 34135911, 2021). "Although this study does not fully evaluate the molecular mechanisms of bone resorption during the periapical lesion, we hypothesize that these results demonstrate the relevance of TLR2 and MyD88 in bone loss from bacterial infection." (PMID 29995146, 2018). "Interestingly, a lethal inflammatory response against IV and secondary bacterial infection was previously linked to TLR2 signalling." (PMID 28195157, 2017). "In addition, animal models have revealed that the defective TLR2 signaling is a causative factor for increased susceptibility to bacterial disease." (PMID 26616674, 2015). "For example, TLR2-/- mice are more susceptible to bacterial infections." (PMID 26214513, 2015). "This may have implications for therapeutic manipulation of equine TLR2, and could potentially indicate altered susceptibility to specific bacterial infections." (PMID 23826682, 2013). "These patients show a decreased cellular response to lipoproteins and TLR2 gene mutations might also predispose for bacterial infections." (PMID 22970242, 2012). "However, it has been implied that TLR-2 deficiency impairs humoral immune responses in case of bacterial infections." (PMID 21674065, 2011). "However, paralysing the TLR-2 -dependent activation of the innate immunity may increase the risk of bacterial infections." (PMID 16606450, 2006). "In summary, bacterial infections have profound effects on sperm function and fertility through the TLR2/4 pathway." (PMID 40242391, 2025).
bacterial infection (continued). "Typically, during planktonic bacterial infections, macrophages are triggered via the classical pathways of toll-like receptors 2 (TLR-2) and 9 (TLR-9)." (PMID 40006601, 2025). "In this context, Pam3CSK4, a triacylated lipopeptide that activates immune responses via TLR2 (toll-like receptor 2), is employed to simulate bacterial infection." (PMID 39960903, 2025). "Pam3CSK4, a triacylated lipopeptide and TLR2 (toll-like receptor 2) ligand, mimics bacterial infection and triggers immune activation." (PMID 39960903, 2025). "Looking at broader bacterial infection pathways such as Toll-like receptor signaling, we observed TLR2 and TLR4 upregulation in Mcat-infected samples and NTHi-infected samples with Mcat apical fluid, likely triggered by Mcat surface LOS or lipoproteins." (PMID 40492732, 2025). "Collectively, these findings suggest that bacterial infections compromise sperm quality via the TLR2/4 signaling pathway." (PMID 40242391, 2025). "Bacterial infections often trigger a multifaceted immune response involving several key pathways, e.g. TLR2 and NFκB signalling, recognizing specific PAMPs such as lipoteichoic acids (LTAs) and peptidoglycans." (PMID 41307706, 2025). "Primary BMDM are naïve macrophages isolated from bone marrow, the birthplace of macrophages in blood and tissues of the whole body, which have been widely used in studies on innate immunity and TLR2/4-mediated NF-κB activation upon bacterial infection." (PMID 38182816, 2024). "All these results suggest that DDX5/METTL3/METTL14-mediated m6A modification suppresses the TLR2/4/NF-κB-mediated inflammatory signaling pathway in vivo during bacterial infection." (PMID 38182816, 2024). "TLR2 recognizes and responds to threats early in bacterial infections and can influence the downstream immune response to the host’s benefit or detriment." (PMID 39080852, 2024). "All these results clearly indicate that DDX5 is a novel inflammation switch, which specifically modulates m6A levels of TLR2/4 transcripts during bacterial infection." (PMID 38182816, 2024). "Unlike DHX29 or DDX19A, which act as viral RNA sensors and activators of inflammation through the NF-κB or NLRP3 pathways, DDX5 regulates the m6A modification of TLR2/4 mRNA to suppress inflammatory responses pathway during bacterial infection." (PMID 38182816, 2024). "Nevertheless, the studies on other bacterial infections demonstrated the downregulation of TLR2 gene via different types of mechanisms." (PMID 39729468, 2024). "TLR2 identifies and responds to initial threats from bacterial infections, subsequently activating downstream immune response which can positively influence the host’s immune response." (PMID 39519462, 2024). "Several other studies on Staphylococcus aureus have also demonstrated the human and mouse TLR2 inactivation during the bacterial infection." (PMID 39729468, 2024). "Lipoproteins, being Toll-like receptor 2 (TLR2) ligands, play a pivotal role in host immune responses to bacterial infection." (PMID 38474151, 2024). "Bacterial infection significantly upregulated mRNA expression levels of Isg15, Mx1, Mx2, Irf-3, Irf-7, Tlr-2, Tnf-α, Cxcl-1, and Il-6 genes." (PMID 37929187, 2023). "Post-immunization analysis of bacterial infection and in the Ischemia model, IgG subclasses in TLR2−/− mice showed a minor increase in IgG1 and IgG2b titers, but a significant decrease in IgG2a titers." (PMID 37258615, 2023). "The TLR2/NFκB signaling pathway’s role in the innate immune response to bacterial infection in conjunction with mycotoxins in the liver is currently unclear." (PMID 37298614, 2023). "Pretreated mice with Pam3CSK4 showed downregulation of TLR2 gene and down-stream molecules IRAK-1(Interleukin-1 receptor Associated kinases) during the bacterial infection." (PMID 38014008, 2023). "Recognition of PAMPs by TLR2 mediates the secretion of pro-inflammatory cytokines that defend against bacterial infection." (PMID 38014008, 2023).